IL15 (interleukin 15)
Diseases named in the same sentence as IL15 in open-access papers (continued):
Sharing a sentence is not in itself a finding about the gene and the disease.
infection (continued). "Furthermore, half of dd CyCMV/SIV-vaccinated MCM controlled SIV replication post infection, and manifested a vaccine-induced IL-15 transcriptomic signature that is associated with efficacy in RhCMV/SIV-vaccinated RM29,30." (PMID 39030218, 2024). "WT and NK cell-deficient Il15-/- mice were then treated with rIFNε prior to infection." (PMID 38263527, 2024). "Administration of IFNγ partially enabled IL-15-deficient mice to control the infection." (PMID 34956227, 2021). "Consequently, it is foreseeable that modified memory CD8+ T cell reactivation during 4X infection was caused by alterations in the levels of IL-15." (PMID 30846985, 2019). "As such, IL-15 MΦ and IL-10 MΦ are differentially identified in the polar forms of leprosy caused by the intracellular bacterium M. leprae, correlating with the different outcomes of infection." (PMID 29965969, 2018). "Indeed, the progressive infection in rhesus macaques is associated with production of IL-15, IL-18, IFN-γ, granulocyte-colony stimulating factor (G-CSF), MCP-1 and macrophage inflammatory protein (MIP)-1β but not in non-progressive sooty mangabeys." (PMID 30568659, 2018). "Although IL-15 SA-treated mice had relatively higher cell counts after wound infection as compared to the respective (day 6) vehicle treated infected mice, infection still caused a significant decline in all the T cell subsets and B cell numbers as compared to IL-15 SA expanded day 4 cell numbers." (PMID 26859674, 2016). "On the other hand, IL-15 SA treatment caused CD8+ T cell activation (~12% CD69 expression) post infection, which was significantly higher as compared to sham (5%) but not statistically different as compared to the vehicle treated burn wound infected group (~8%)." (PMID 26859674, 2016). "Importantly, while the numbers of NK cells were significantly reduced at the site of infection as a result of an IL-15 deficiency, anti-IL-15 treatment had little effect on the frequency or number of NK cells found in anatomical sites distal to the site of infection such as the spleen." (PMID 22624047, 2012). "This systemic response was followed by an increase in additional inflammatory cytokines such as LIF, GM-CSF, and IL-15 at the peak of infection." (PMID 41472308, 2025). "Suggestive of the involvement of T cell dynamics in the persistent inflammation following the Spn infection phase, we observed elevated levels of IL-15, which induces proliferation and activation of T cells in Spn-surviving humans." (PMID 41073563, 2025). "The marked upregulation in central memory CD8+ T cells and IL-15 secretion in WT mice following infection suggests a role for these cells in P. aeruginosa clearance." (PMID 40512037, 2025). "Although transcription of IL-1α, IL-1β, IL-6, and IL-15 genes was substantially upregulated, overall cytokine responses to infection with VR-2332 were insignificant." (PMID 40302751, 2025). "Infection was associated with the upregulation of proinflammatory genes CXCL10, IFNG, and IL15, alongside several NK and T cell activation markers such as CD244, CD40LG, and CD226." (PMID 39774119, 2025). "While there was a slight increase in IL-15 secretion (5 ± 2 vs. 8 ± 3 pg/mL) and IL-10 (1.4 ± 2.0 vs. 2.3 ± 2.5 pg/mL) upon infection, IL-8 and IL-1β remained unchanged." (PMID 41239423, 2025). "Animals that met endpoint criteria and were euthanized following exposure to NiV-M had rapidly increasing levels of IL-1RA, IFN-γ, IL-15, and IL-2, similar to what was seen in animals with NiV-M infection following intermediate particle exposure." (PMID 41460894, 2025). "This was especially apparent for IL15, which was specifically expressed in female macrophages upon infection." (PMID 40794782, 2025). "IL-15 was also shown to impact the composition of the secondary TMEM pool in response to infections." (PMID 38405398, 2024).
infection (continued). "We show that rIFNε and rIL-15 have similar effects on NK cell accumulation during infection in WT mice, consistent with IFNε mediating this NK cell response through the actions of IL-15 in vivo." (PMID 38263527, 2024). "We also show the mechanisms by which IFNε primes for NK cell responses to infection are through driving the accumulation of NK cell progenitors and the expression of IL-15 in the uterus and by directly stimulating NK cell activation." (PMID 38263527, 2024). "Although IL-15 is an essential homeostatic cytokine, it also plays a key role in triggering effector T-cell responses in infection and sterile inflammation." (PMID 38405398, 2024). "Il15 transcript expression is reduced in Ifne-/- mice (~40%) at baseline (p = 0.056) and during infection (p = 0.076) compared to WT mice." (PMID 38263527, 2024). "Functionally, NKB cells have been described as expressing several cytokines, including IL-1b, IL-6, IL-12, and IL-15, upon stimulation/infection, in addition to their signature IL-18 secretion." (PMID 38739675, 2024). "In tissues, IL-15 is upregulated in infection and stress, and can drive the cytotoxic effector functions of tissue-resident T cells, a key function for protecting the tissue against pathogens." (PMID 38405398, 2024). "Including lymphoid lineage by cytokines presumably IL-7 and IL-15 with longer-term incubation would recapitulate the infection and downstream inflammatory events more precisely." (PMID 38627497, 2024). "As expected, we observed an increase in neutrophil, monocyte, and NK cell recruitment cytokines CXCL10, CCL5, and IL-15 during SEOV infection in Cas9 WT control HUVEC." (PMID 39585900, 2024). "To confirm the role of IFNε in inducing IL-15 and NK cell responses, we then performed gain-of-function studies in WT mice by transcervical and intravaginal administration of rIFNε prior to infection (Fig. EV4A,B)." (PMID 38263527, 2024). "To then gain insights into germinal center cytokine effects on EBV-infected primary B-cells, we treated cells at 7 days post-infection with vehicle control, IL-4, IL-15, IL-21, IL-27 or multiple combinations thereof." (PMID 38683861, 2024). "The amount of IL-15 also increased by approximately 50% after infection with Mtb, which is significantly less than the mRNA level, suggesting posttranscriptional control." (PMID 37781389, 2023). "As expected, CD4+ T cells pretreated with IL-15 had a higher percentage of infection by a CCR5-tropic HIV-1 reporter virus." (PMID 36821374, 2023). "Our data suggest Theracurmin has an immunomodulatory (CCL2, IL-15, CK and tissue leukocyte infiltration) and a trypanocidal effect (on circulating parasites) during experimental infection triggered by the Colombian strain of T." (PMID 37505639, 2023). "Key innate inflammatory cytokines, including TNFα, IL-6, IFNα, IL-10, IL-15, and IL-18, were all significantly elevated early during infection (days 1–5) compared to HCs." (PMID 36752598, 2023). "Importantly, both IL-15 and IL-20 have been implicated in fibrosis, suggesting that Chlamydia-infected endocervical epithelial cells may produce a wider portfolio of fibromodulatory cytokines relative to infection of other cell types." (PMID 37874141, 2023). "IL-15 and IL-11 are key cytokines reported to take a critical part in the regulation of infection and inflammation." (PMID 36742132, 2023). "Both IL-12 and IL-15 are known activators of NK cells, which control infection through the secretion of perforin and granzyme B and production of IFN-γ and TNF-α." (PMID 37261350, 2023). "IL-12 and -18 induce IFN-γ production, possibly contributing to early infection control, whereas IL-15 equips memory CD8+ T cells to produce cytotoxic molecules like granzyme B and perforin." (PMID 36951943, 2023). "Plasma levels of IL-4, IL-7, and IL-15 were similar at acute infection and 3 months but declined at later time points, suggesting a slow recovery of T-cell-related perturbations within 12 months." (PMID 37310006, 2023).
infection (continued). "In two HIV mice models IL-15-primed CD8+ T cells showed enhanced in vivo activity on initial viremia when given at the day of infection, but administration of an IL-15 superagonist led to increased plasma viral set-point." (PMID 37767312, 2023). "We observed that the overall rate of infection was increased in cells stimulated with IL-15 compared to cells stimulated with IL-2." (PMID 35499323, 2022). "On the other hand, the percentage of latently infected cells with respect to total infection was diminished by IL-15 stimulation in all the memory subsets analyzed (TCM, TEM, and TTM)." (PMID 35499323, 2022). "To analyze latency establishment more quantitatively, we determined the outcome of infection in each subset in IL-2 or IL-15 conditions." (PMID 35499323, 2022). "The most interesting cytokine in the context of T. cruzi infection in this study was IL-15, which is also strongly induced by the infection and remains at a very high level throughout the course of the infection." (PMID 35720419, 2022). "IL-15 stimulation increased the overall infection for all the more differentiated memory subsets (TCM, TEM, and TTM)." (PMID 35499323, 2022). "A recent study demonstrated that NK cells stimulated with IL-12 and IL-15 were capable of controlling SARS-CoV-2 following infection of VeroE6 or Calu3 cells." (PMID 35587364, 2022). "Infection of mice led to common epitope variants between S-QIIV and Wyeth/IL-15/5Flu vaccination conditions." (PMID 35385318, 2022). "The average distribution of all CD4+ T cell subsets was similar in the different conditions, with a decrease in Temra cells in the IL-15 condition after infection." (PMID 35499323, 2022). "Cytokines transcriptional trends revealed an immunosuppressive response during early infection stages, with decreased expression of some cytokines, such as IL-12, IL-4, IL-5, IL-1, IL-18, and IL-15, at 2 dpi, 4 dpi, or both compared to control." (PMID 36187827, 2022). "We next compared the overall infection and latency establishment under IL-2 or IL-15 stimulation for all the CD4+ T cells subsets." (PMID 35499323, 2022). "We next determined the percentage of latently infected cells with respect to total infection in each subset for the IL-15 condition." (PMID 35499323, 2022). "In line with previous reports, we observed that when CD4+ T cells are stimulated with IL-15, the global levels of infection increase compared to IL-2 treatment." (PMID 35499323, 2022). "We have previously shown in this work that the higher levels of pTEFb expression upon IL-15 stimulation correlated with higher levels of productive infection than IL-2." (PMID 35499323, 2022). "During 3 h, 5 h, and 7 h of infection in HKDM-WT production of IL-15 significantly increased compared to uninfected HKDM, and significantly decreased in HKDM-∆EseN compared to HKDM-WT." (PMID 35889053, 2022). "Even though several studies have established a role for IL-15 in conferring protection against infections, few have addressed the role of IL-15Rα in pathogen control." (PMID 34956227, 2021). "By days 5 and 7 of infection, there was a marked difference in gene expression with heightened expression of Mx1, Tlr3, Ifnα2, Ifnαr1, Ifnβ1, and Il-15 detected in aged lung in response to H1N1." (PMID 34829979, 2021). "Here, we demonstrated that the infection of microglia with an AAV-serotype 2 carrying IL-15 functionally induces the release of IL-15." (PMID 34552593, 2021). "The animals vaccinated with this regimen were still susceptible to intravenous infection with SHIV89.6P, but animals that received plasmid IL-15 controlled infection more quickly than the group treated with DNA vaccine alone." (PMID 34578331, 2021). "While some expression patterns remained elevated during infection, by day 5 there was increased Il-12a, Il-12b, Il-6, Cd80, and Cxcl11 expression that corresponded with elevated Il-15 levels in young adult H1N1 and H3N2 infected lung." (PMID 34829979, 2021).
infection (continued). "Although not statistically significant, we observed that the early appearance of several pro-inflammatory cytokines and chemokines (TNFα, MCP-1, IL15, and G-CSF) were more associated with ZIKV-Brazil and/or ZIKV-FP infections." (PMID 34120576, 2021). "At 5 days post infection (dpi), female WT mice were able to control the infection and showed reduced bacterial load in spleen and the liver, whereas female Il15-/- mice showed high bacterial counts in these tissues." (PMID 34956227, 2021). "The fraction of bacteria present within BMDMs was comparable between WT and Il15-/- cells 4 hours post-infection (hpi)." (PMID 34956227, 2021). "This higher response to IL-15 stimulation in the Themis–/– mice indicates the potential of Vα3.2+ T cells to be bystanders, which help the antigen specific cells during an infection." (PMID 33897691, 2021). "Acute HIV/SIV infection is characterized by immune activation, and studies have shown that IL-15 can enhance HIV replication in addition to antigen-induced lymphocyte proliferation." (PMID 34578331, 2021). "Non-antigen specific bystander T cells become activated by the cytokines produced during an infection, such as IL-15 induced by type I interferons." (PMID 33897691, 2021). "Fusion proteins IL-15GFP and IL-15RαGFP were also constructed to analyze the BV infection and the expression of IL-15, IL-15Rα, or the IL-15:IL-15Rα complex at the single-cell level." (PMID 34439192, 2021). "Reconstitution of Il15-/- mice with WT or Il15ra-/- BM was sufficient to control the bacterial load, and Il15ra-/- mice harboring Il15-/- BM cells still controlled the infection." (PMID 34956227, 2021). "IFNγ treatment reduced the bacterial load in the spleen to a modest level and almost completely in the liver of Il15-/- mice, suggesting that impaired early IFNγ production plays a crucial role in the control of the infection." (PMID 34956227, 2021). "In our analysis, after infection diagnosis in susceptible dogs, PGE2 correlated with TNFα, IL-2, IL-15, and IL-7, most of them with pro-inflammatory functions, possibly attempting to decrease the inflammatory immune response." (PMID 33617528, 2021). "IL-15 levels elevate to a peak at day 10 post-infection and subsequently decline by day 14 post-infection." (PMID 34578331, 2021). "In response to H1N1 or H3N2, there was increased expression of Il-15, Tlr3, and Stat1 detected in young lung at day 7 of infection." (PMID 34829979, 2021). "Endogenous IL-15 had an important function in early protection against infection with an avirulent strain of S. choleraesuis through the activation of NK cells and IFN- γ production." (PMID 34943999, 2021). "We propose that the differential sensitivity of distinct CD8+ T cell subsets to IL-15 exacerbates its effects in states of increased IL-15 production, such as infection or ageing." (PMID 32504069, 2020). "Abrogating IL-15 signalling during infection was sufficient to abrogate the infection-driven increase in SRC in TVM cells." (PMID 32504069, 2020). "Enhanced levels of IL12 and IL15 were observed after infection in PBS NC99 mice, which is the group that had high levels of TRM in the lungs." (PMID 32582220, 2020). "IL-15 is produced at low levels in the steady state but it can be dramatically upregulated in DCs during infection, in response to type I IFN signalling." (PMID 32504069, 2020). "IL-15 is produced at low levels in steady state but can be dramatically upregulated in DCs during infection in response to type I IFN signalling." (PMID 32504069, 2020). "Although the T cell depleted mice eventually succumbed to infection, IL-15 significantly reduced virus spread and prolonged survival relative to control mice, supporting a role for the early expansion of NK cells in protection." (PMID 32320436, 2020). "The NK cell-activating cytokines, interferon-α (IFNα), IL-12, and IL-15, were significantly elevated during the acute phase of infection, but the detected levels were relatively low." (PMID 31467285, 2019).
infection (continued). "Dam 3 exhibited an increase above baseline in IL-2, IL-6, IL-7, and IL-15; notably, all cytokines increased on day 7 and returned to basal by day 14 post-infection." (PMID 30657788, 2019). "Dam 2 had an increase in IL-1β, IL-2, IL-6, IL-7, IL-12, IL-15, IL-16 and IL-17A, peaking on day 14 post-infection for all but IL-12 and IL-15 which peaked on day 7 post-infection." (PMID 30657788, 2019). "Early in infection, NK cells are activated by cytokines such as type I interferons, interleukin-12 (IL-12), IL-15, and IL-181–3." (PMID 31467285, 2019). "Levels of IL-15, a cytokine that stimulates NK cell proliferation, were elevated above baseline 6–12 days post-infection but were lower than in other animals during the same time frame." (PMID 31166946, 2019). "IL-15 boosts the immune response to infection by activating NK cells and enhancing priming of CD4/CD8 cells in terms of IFN–r production in patients with TB." (PMID 30760247, 2019). "Strikingly, IL-15-mediated depletion of NK cells in chronic SIVagm infection led to high viral replication in the follicles as well as in the T zones." (PMID 29725327, 2018). "Results from these analyses indicated that sagA complemented GAS induces a 2-fold or greater increase in I-309, IL-1α, IL-1β, IL-2, IL-15, MCP-3, MIG, and MIP-1δ compared to the SLS-deficient mutant infection." (PMID 30018884, 2018). "Mice with IRF4 deficient CD11c+ cells had less secretion of IL-4, IL-15 and IL-13 after immunization with OVA and papain as well as during infection with the nematode Nippostrongylus brasiliensis." (PMID 29343807, 2018). "Because macrophages and DCs are able to produce large amounts of IL-15 and IL-18, we analyzed IL-15 and IL-18 mRNA levels in splenocytes from FV-infected and Treg depleted animals during initial infection." (PMID 30210499, 2018). "To prove that the cytokines IL-15 and IL-18 contribute to the cytotoxic functions of NK cells after high-dose FV challenge, we neutralized both cytokines during infection." (PMID 28904191, 2017). "In contrast, triggering the activity of T helper 2 along with secretion of IL-4, IL-10 and IL-15 enhances the durability of infection." (PMID 28979355, 2017). "At the initial infection, macrophages infected by T. gondii tachyzoites produced interleukin (IL-2), tumor necrotic factor-α, IL-β, and IL-15." (PMID 29062190, 2017). "During infections, DCs release a variety of cytokines, such as type I IFNs, interleukin 12 (IL-12), IL-15, and IL-18, that strongly influence NK cell responses." (PMID 28904191, 2017). "NK cell proliferation as well as IL-15 and IL-18 release by macrophages and DCs occurs early during infections." (PMID 28904191, 2017). "It has been shown that NK cells become ‘primed' upon exposure to cytokines such as IL-2 or IL-15 and, in turn, have enhanced reactivity against target cells, a situation that likely occurs during the course of infection and transformation." (PMID 27221592, 2016). "One effective approach is to modulate the crosstalk between NK cells and dendritic cells, which produce NK cell-stimulating cytokines like type I interferons (IFN), IL-12, IL-15, and IL-18 upon retrovirus sensing or infection." (PMID 27821119, 2016). "IL-15 can be induced by various stimuli including endotoxin, interferons α/β/γ, double stranded RNA, and infection with viruses." (PMID 26859674, 2016). "Infection also caused a significant increase in the levels of plasma KC and MIP-2 and MIP-2 concentrations were higher in IL-15 SA-treated mice than in vehicle controls." (PMID 26859674, 2016). "IL-15 induced following infection can activate the inflammatory cascade by stimulating the expression of chemokines in the infected tissues while inhibiting energy wastage by thermogenesis in BAT, as shown in this study." (PMID 27684068, 2016). "During many infections myeloid DCs secrete IL-12 or IL-15 that potently induce NK cell activation and proliferation." (PMID 27821119, 2016).